NOS2 (nitric oxide synthase 2)
Diseases named in the same sentence as NOS2 in open-access papers (continued):
Sharing a sentence is not in itself a finding about the gene and the disease.
Thrombocytopenia (1 paper, 2012). A reduction in the number of circulating thrombocytes. "Of note, infected IFN-γ-deficient and NOS2-deficient mice presented heightened viral replication, in parallel with elevated hematocrits, thrombocytopenia, and liver injury." (PMID 22666512, 2012).
Tinnitus (1 paper, 2025). Tinnitus is an auditory perception that can be described as the experience of sound, in the ear or in the head, in the absence of external acoustic stimulation. "For example, TLR4 is targeted by cyclobenzaprine, which is currently used to treat tinnitus, NOS2 can be targeted by dexamethasone and gingko biloba, which are also already used to treat tinnitus." (PMID 40217670, 2025). "NOS2 can also be targeted by arginine, miconazole, and minocycline, which could theoretically be repurposed for the treatment of tinnitus." (PMID 40217670, 2025).
trichotillomania (1 paper, 2018). A disorder characterized by repetitive pulling out of one's hair resulting in noticeable hair loss; the individual experiences a rising subjective sense of tension before pulling out the hair and a sense of gratification or relief when pulling out the hair. "The present study suggests that the increased barbering behavior (BB) of NOS2 KO mice could be a putative model of trichotillomania (TTM)." (PMID 29682419, 2018).
uremia (1 paper, 2025). A clinical syndrome associated with the retention of renal waste products or uremic toxins in the blood. "Among them, HMOX1, SOD2, and NOS2 have become the key targets - which is consistent with their previous research that can protect renal tubules from oxidative damage, maintain mitochondrial antioxidant capacity, and regulate the oxidative-reductive imbalance associated with uremia." (PMID 41560720, 2025).
urolithiasis (1 paper, 2023). Stone(s) within the urinary tract. "Unfortunately, none of the studied haplotypes were significantly associated with urolithiasis in the case of IL-6 and NOS2 genes." (PMID 37878647, 2023). "Moreover, we have performed an additional analysis of IL-6, IL-8, SOD2, and NOS2 expression in the genotype groups of controls and patients with urolithiasis." (PMID 37878647, 2023). "In conclusion, our results suggest that polymorphic variants and changes in mRNA expression of IL-6, IL8, SOD2, and NOS2 may be involved in the pathophysiology of urolithiasis." (PMID 37878647, 2023). "Moreover, we verified the association of urolithiasis development and mRNA expression of IL-6, IL-8, SOD2, and NOS2 in peripheral blood mononuclear cells (PBMCs)." (PMID 37878647, 2023). "In turn, in the case of NOS2 expression in PBMCs, we also found no statistical decrease in patients with urolithiasis as compared to controls." (PMID 37878647, 2023).
visceral leishmaniasis (1 paper, 2018). A severe form of leishmaniasis characterized by irregular bouts of fever, substantial weight loss, swelling of the spleen and liver, and anemia (which may be serious). "In preclinical models of visceral leishmaniasis, the impact of local oxygen levels on Nos2-mediated antileishmanial defense and NO production in the spleen and liver is, however, to the best of our knowledge unexplored." (PMID 29520262, 2018). "Compared to the role of Nos2 in the defense against visceral leishmaniasis in the liver, the contribution of Nos2 in the control of parasite load in the spleen in visceral leishmaniasis is less pronounced." (PMID 29520262, 2018). "Moreover, in mouse models of visceral leishmaniasis, Nos2 expression is important for control of L. donovani in the liver, and contributes to the containment of L. donovani in the spleen." (PMID 29520262, 2018).
ZIKV infection (1 paper, 2021). "It has been reported that some genes, such as TNF, NOS2, PTGS2, and VEGFA, as well as their proteins, are overexpressed during ZIKV infection, acting on the inflammatory response mechanism." (PMID 33672623, 2021). "We highlight that the NOS2 gene haplotypic frequency was different between the two groups of children who were in utero exposed to ZIKV infection; however, it has not reached statistical significance, probably due to the sample size of the groups." (PMID 33672623, 2021).
α-synucleinopathy (1 paper, 2023). "Overall, our results suggest that NOS2 is a crucial regulator of the synucleinopathy and neuroinflammatory response associated with PD pathology." (PMID 36647152, 2023). "The significant reduction in p-Synser129 levels in SynA53T/NOS2−/− mice compared with SynA53T mice suggests that decreasing NOS2 expression may help alleviate α-synucleinopathy in the brain." (PMID 36647152, 2023).
tumor (386 papers, 1995 to 2026). "In CRC, high NOS2 levels are strongly associated with tumour invasion, metastasis, and resistance to chemotherapy, and serve as an independent adverse predictor of both overall and recurrence-free survival." (PMID 41174721, 2025). "Considering the interplay between systemic immune cell ratios and the tumor microenvironment, particularly their association with the NOS2/ARG1 axis and tumor-infiltrating lymphocytes, we next explored the clinical relevance of these markers." (PMID 41573553, 2025). "Nos2 has been demonstrated to promote NO synthesis, tumor death, and increasing pathogenic microorganisms, secreting a large number of pro-inflammatory factors, including IL-1β, C-X-C motif chemokine ligand 1 (CXCL1), and others." (PMID 40002899, 2025). "NOS2 was primarily expressed at the tumor margin, whereas COX2 together with B7H4 was associated with immune desert regions lacking TEff cells, where a higher ratio of tumor NOS2 or COX2 to TEff cells predicted poor survival." (PMID 40663402, 2025). "The up‐regulated genes in tumor‐infiltrating myeloid cells in RARα‐KO mice included Rnf128, Cd36, Nos2, Prdx1, Cd274, and H2‐Q4, associated with the immune‐activating phenotype." (PMID 40068101, 2025). "While COX2 inhibition limited tumor growth, NOS2 deficiency was critical for increased cure rates due to augmented antitumor B cell phenotypes associated with Nos2 depletion." (PMID 40663402, 2025). "The distribution of tumor cells was mainly associated with NOS2+/– edges as well as tumor satellite and tumor core regions." (PMID 40663402, 2025). "High NOS2/COX2-expressing tumors exhibited increased IDO1 clustering that was more closely associated with tumor margins proximal to elevated NOS2Tumor regions, while low expression was observed in immune desert regions in deceased patient tumors." (PMID 40663402, 2025). "COX2 was significantly higher in association with the NOS2+ tumor edge but was also found in the tumor core and stroma-restricted lymphoid aggregates." (PMID 39356141, 2024). "Our study also showed that high-NOS2 expression was associated with poor prognosis in patients with HB, unfavorable anti-tumor immune response, and resistance to cisplatin therapy." (PMID 37795447, 2023). "Another study indicated that 8-hydroxyguanine (8-OHG) released from ferroptotic cells recruits and activates tumor-associated macrophages (TAMs) to secrete IL-6 and nitric oxide synthase 2 (NOS2), promoting tumorigenesis of KRAS-driven PDAC." (PMID 35664778, 2022). "More and more studies indicated that NOS2 expressed in tumor-infiltrating immune cells such tumor associated macrophages (TAMs) and myeloid-derived suppressor cells (MDSCs) play a critical role in cancer immune modulation." (PMID 35538490, 2022). "Tumor gene expression analysis performed 7 days post Imprime dosing showed upregulation of M1 markers, e.g., Nos2, Il12b, and Tnfa, along with downregulation of M2-associated genes including Arg1 and Ccl17." (PMID 35692755, 2022). "Further, HIF-1α activates the transcription of genes encoding transferrin, VEGF, endothelin-1, and inducible nitric oxide synthase (NOS2), which are implicated in vasodilation, neovascularization, and tumor metastasis." (PMID 34178680, 2021). "In fact, HEIH reduces miR-939-5p expression, which is associated with the upregulation of NOS2-dependent NO generation and tumor promotion in TNBC (Figure 3B1)." (PMID 34200849, 2021). "On the other hand, given the versatility of NOS2, its deregulation has been implicated in tumor progression." (PMID 34200849, 2021). "On the other hand, NOS2 has been implicated in macrophage-mediated anti-tumoral activity in various human tumors through inhibition of tumor growth and metastasis." (PMID 33036138, 2020).
tumor (continued). "While iNOS is commonly considered as being anti-tumorigenic, NOS2 has been implicated as a contributor to the process of tumor initiation and/or development, especially when the concentrations of its product, NO, are low." (PMID 32355198, 2020). "Upregulated genes such as those encoding Arg1 and nitric oxide synthase 2 (NOS2) seem to confirm an immunosuppressive tendency of tumor progression." (PMID 32488850, 2020). "In vivo PDE5 inhibition reduced ARG1 and NOS2 and down-regulated IL-4Rα in tumour-associated MDSCs in BALB/c and C57BL/6 tumour-bearing mice." (PMID 29743944, 2018). "This dichotomy originates from the observations that the inducible form of NO synthase (iNOS or NOS2) was implicated in the macrophage-mediated tumor killing process." (PMID 30234010, 2018). "Tumor associated macrophages (TAMs) can also produce nitric oxide within the tumor site through the activation of nitric oxide synthase 2 (NOX2)." (PMID 26682014, 2016). "Primary tumor cells isolated from NOS2-deficient KPC (NKPC) mice showed decreased proliferation and invasiveness as compared to those from KPC mice." (PMID 27367029, 2016). "Next we determined if the NOS2-deficiency affected the migratory and invasive properties of primary tumor cells." (PMID 27367029, 2016). "There was uniform upregulation of this gene cluster (which included Adc, Nos2, Ass1, Gch1, Asl and Got1) in both tumor-associated MP and MG and Gr1+ cells." (PMID 27936099, 2016). "NOS2 is associated with M1 macrophages and is upregulated in the tumor microenvironment of TAMs and TANs and during tumor progression." (PMID 27851813, 2016). "NF-κB association with the NOS2 promoter chromatin was detected in three regions of the NOS2 promoter region in TNFα-treated tumor cells." (PMID 26497740, 2015). "Subsequent functional analyses and results from in situ studies of GCPs in postnatal cerebellum allowed us to formulate a model for the tumor promoting role of Nos2 deficiency in Ptch1 mutant mice via deregulation of Gap43-dependent migration of GCPs." (PMID 22438824, 2012). "A strong inverse association with tumor stage was found for both NOS2+ (P<0.0001) and CD163+ (P<0.0001) macrophage infiltration." (PMID 23077543, 2012). "In human tumors, sustained NOS2 expression in cancer cells and tumor-associated macrophages (TAMs) enforces a Warburg-like state characterized by high glycolytic flux, glutamine dependence, and enhanced NADPH production, supporting proliferation, biosynthesis, and resistance to oxidative stress." (PMID 42248132, 2026). "Prior studies have shown that NOS2 is predominantly associated with the tumor epithelium." (PMID 40663402, 2025). "Tumors also contained numerous intermingling CD68+ and PDL1+ macrophages that were significantly elevated in lymphoid aggregates and the NOS2+ tumor edge, while COX2+ macrophages were associated with NOS2+ tumor edges when compared with the tumor core and/or tumor satellite regions." (PMID 40663402, 2025). "This apparent dichotomy of IFN-γ activity between tumor eradication (facilitated by host antitumor immune responses) and NOS2/COX2-associated immunosuppression implicates it as a key modulator in a delicate balance between tumor immune surveillance and immune evasion." (PMID 40663402, 2025). "NOS2 has initially been reported to play a significant anti-tumor role in the immune response; however, growing evidence has demonstrated that the expression level of NOS2 in tumor cells is usually associated with impaired prognosis." (PMID 38178187, 2024). "Hence, increased NOS2 expression is indicative of an increased risk for an unfavorable anti-tumor immune response." (PMID 37795447, 2023). "Considering that NOS2 was one of the most significantly affected FRGs in our model and the most obvious expression differences between patients in high risk and low risk groups, we further investigated the role of NOS2 in ferroptosis-related tumor progression." (PMID 37346068, 2023).
tumor (continued). "Furthermore, tumor sEVs also inhibited oxidative phosphorylation in tumor-associated macrophages by upregulating NOS2 expression, and administration of the NOS2 inhibitor S-ethylisothiourea hydrobromide restored oxygen utilization." (PMID 36588730, 2022). "M1 macrophage marker NOS2 can activate macrophages and causes tumor cell death." (PMID 34733886, 2021). "However, in tumor environment, MDSCs not only have characteristics of M2 macrophages (such as the expression of arginase-1 and NOS2), but also play a role as the progenitor cells of tumor associated macrophages." (PMID 33154947, 2020). "We report that the acquisition of tumor aggressiveness in patients is dependent on close associations prevailing between NOS2 and IL-10 synthesis and between IL-17A, TGF-β, and MMP-9 and identifies IL-17A as a possible key predictor of LSCC aggressiveness and resistance to therapy." (PMID 31885577, 2019). "Additionally, we took advantage of Nos2-deficient mice which we inoculated with MCA205WT tumor cells." (PMID 31481761, 2019). "For the tumor-associated macrophage populations, this analysis revealed high expression of the alternative activation markers Arg1, Fizz1, and Mrc1, which coincided with reduced mRNA levels of the classically activated marker Nos2." (PMID 31227713, 2019). "Similar to our results in naïve mice, we found a strong downregulation of Nos2 expression in Stat1 deficient M1 macrophages derived from tumor bearing mice as well as decreased secretion of soluble TNFα in the supernatant derived from M1 macrophages differentiated from tumor bearing STAT1 KO mice." (PMID 30647851, 2018). "Additionally, a significantly lower number of PanIN-1 lesions and absence of any carcinoma in NKPC mice as compared to the KPC mice, of which 30 percent (2 out of 6) showed the presence of carcinoma at an early age of 6 week, indicated an increased tumor-latency in NOS2-deficient NKPC mice." (PMID 27367029, 2016). "The mechanistic basis for why tumor progression is sometimes associated with NOS2 expression is not fully understood, but could include additional mutation by NOS-mediated DNA strand breakage, and immunosuppression of T-cell responses through both NO-dependent and NO-independent mechanisms." (PMID 25346730, 2014). "Therefore, it remains to be seen whether the up-regulation of NOS2 in line 72 could induce immunosuppression and increase the risk of tumor generation in MD-susceptible chickens." (PMID 21992110, 2011). "Quantitative spatial analysis has revealed NOS2/COX2 roles during the temporal progression from immune hot in low COX2 expressing tumors to three immune cold stages in the tumor microenvironment of high COX2 expressing tumors." (PMID 42097035, 2026). "Type 1: immune cold with stroma-restricted CD8+ T cell secretion of interferon gamma, which activates COX2 expression at the tumor margin as well as NOS2 expression at the tumor periphery." (PMID 42097035, 2026). "Type 3: mature immune desserts exhibit abated NOS2, COX2 and CD8+ T cells, and induction of B7H4 and cancer-associated fibroblasts driven by significant tumor hypoxia and necrosis." (PMID 42097035, 2026). "Increased NOS2-derived NO promotes metastasis, where higher clustering of NOS2+ tumor cells leads to increased oncogenic pathway signaling and immune-modulatory proteins, including IL-1, IL-6, IL-8, and TNF-α." (PMID 40663402, 2025). "Patients with elevated NOS2 expression exhibit increased tumor invasiveness and reduced survival, likely due to NO-mediated inflammation and angiogenesis." (PMID 40642105, 2025). "This suggests that NOS2-driven NO production enhances tumor aggressiveness, making it a robust prognostic marker." (PMID 40642105, 2025).